OCLN (occludin)
Diseases named in the same sentence as OCLN in open-access papers (continued):
Sharing a sentence is not in itself a finding about the gene and the disease.
colitis (continued). "In the colitis group, decreased occludin and ZO-1 immunopositivity was observed." (PMID 39105785, 2024). "However, occludin and ZO-1 immunopositivities were higher in the colitis + DHA group than in the colitis group." (PMID 39105785, 2024). "A study has confirmed that Baitouweng Decoction could elevate the levels of ZO-1, Occludin, which are beneficial to repairing colonic barrier in colitis mice by means of regulating AMPK/mTOR-mediated autophagy." (PMID 39351096, 2024). "This study demonstrates that DSS-induced colitis leads to a decrease in Occludin and ZO-1 proteins." (PMID 39329121, 2024). "Furthermore, Gpr81 knockout resulted in increased protein expression of MMP9 and decreased expressions of Claudin-1, ZO-1, and Occludin in the colitis mice." (PMID 38474712, 2024). "Sesamol and apigenin could increase the expression of Occludin, claudin-1, and Zo-1 to attenuate colitis." (PMID 37887381, 2023). "In Caco2 cells, docosahexaenoic acid (DHA) limited the effect of the inflammatory stimulus on occludin, ZO-1 and barrier function, inhibited the NF-kB pathway and ameliorated experimental colitis in IL-10-/- mice, improving intestinal epithelial barrier function." (PMID 36839239, 2023). "Similarly, the gut barrier function was impaired in mice with colitis, but the mRNA expression of tight-junction proteins ZO-1 and Occludin was increased in the MH1 and ZJ1 groups." (PMID 38067023, 2023). "Our research showed that Fp-EVs could increase the expression of ZO-1 and Occludin in the colons of DSS-induced colitis mice to some extent." (PMID 37968625, 2023). "We also found that mouse P2Y1R deficiency in mice significantly reduced goblet cell loss and intestinal permeability; increased the levels of tight junction proteins occludin, claudin-3, and ZO-1; and decreased claudin-2 in the colon tissues of mice with colitis." (PMID 37781034, 2023). "The result showed that Occludin and Claudin-1 mRNA were significantly upregulated in Parkin-/- mice, suggesting that loss of Parkin has a protective effect in DSS-induced colitis." (PMID 37056928, 2023). "Occludin, Claudin-1 and ZO-1 are intestinal epithelial tight junction marker proteins, and ZO-1 and Occludin were considered as valuable predictive proteins for the severity of colitis and mucosal healing." (PMID 36766197, 2023). "Moreover, Western blot analysis showed that the decreased expression of ZO-1 and occludin in DSS-induced colitis was recovered by the Polycan treatment." (PMID 37834221, 2023). "Our study showed that the newly isolated C4 strain could effectively reduce the expression levels of IL-1β, IL-6, and TNF-α, and upregulate the expression levels of ZO-1 and occludin to alleviate the symptoms in DSS-induced colitis mice." (PMID 37152759, 2023). "Similarly, the downregulation of tight junction protein expression, including claudins, occludin, and ZOs, is also seen in experimental models of colon inflammation induced by dextran sodium sulfate." (PMID 37049744, 2023). "Besides, ZO-1, Claudin-1, and Occludin have been classified as fundamental tight junction proteins and their repression elicited potential in the alleviation of colitis." (PMID 36890151, 2023). "In a colitis mouse model, SA was found to enhance the expression of ZO-1, occludin, and claudin-1." (PMID 37444374, 2023). "One of colitis treatment strategies is TJ protein, including ZO-1, occludin and claudin, which lead to protection of intestinal mucosa barrier from the infiltration of harmful substances or bacteria by anchoring with actin cytoskeleton and tightly sealing the epithelium." (PMID 37111064, 2023). "Moreover, IF staining results were consistent with Western blotting results and showed that the decreased expression of ZO-1 and occludin in DSS-induced colitis was recovered by FGR treatment." (PMID 36829894, 2023).
colitis (continued). "Therefore, it is particularly crucial to determine the effect of L. gasseri JM1 on the mRNA expressions of intestinal tight junction proteins (Claudin-2, Claudin-3, Occludin and ZO-1) in mice with colitis." (PMID 36615796, 2022). "Moreover, immunofluorescence staining indicated that DSS-induced colitis downregulated the protein expression of ZO-1 and occludin in the colon (P < 0.01 or P < 0.05)." (PMID 36424592, 2022). "Furthermore, corylin, at a dose of 100 mg/kg (H), significantly increased the levels of claudin-1 and occludin, which were even higher than for the effects produced by corylin at a dose of 25 mg/kg (L) compared with colitis mice." (PMID 35269806, 2022). "In support, glucosamine was able to reduce colitis-associated symptoms in DSS-treated mice by reducing TNF-α, IL-1β, and NF-kB expression in the colonic mucosa, and increasing the expression of ZO-1 and occludin tight junction proteins." (PMID 36009057, 2022). "Furthermore, protein expressions such as TLR4, MyD88, p–NF–κB-p65, NF-κB-p65, COX-2, ZO-1, and Occludin were detected to elucidate the molecular mechanism of Jat on DSS-induced colitis model." (PMID 36193153, 2022). "In DSS-induced colitis in mice, intestinal permeability increased significantly, and tight-junction proteins occludin, claudin 1 and claudin 3 that are closely related to intestinal permeability decreased, whereas RJ significantly improved the changes of intestinal permeability." (PMID 35631210, 2022). "Occludin is one of the major intestinal tight junction proteins involved in maintaining the structural integrity of the colon, and is observed to be downregulated during colitis." (PMID 35529468, 2022). "longum DD98 could also enhance tight junction protein expression, such as ZO-1 and Occludin, thus improving the intestinal barrier integrity in colitis mice." (PMID 35992694, 2022). "After colitis onset, treatment with MSPNPs was more effective than that with free MSPs in restoring the expressions of tight-junction-related genes (upregulation of occludin, ZO-1, JAM, MUC and FABP-2) and beneficial gut microbiota." (PMID 35745756, 2022). "Repeated electroacupuncture could improve DSS-induced colitis, repair TJ damage (both claudin-1 and occludin) and inhibit proinflammatory mediators." (PMID 36101343, 2022). "In the present study, whether at the gene or protein level, treatment with BPIS upregulated the expression of Claudin-1, Occludin, and ZO-1 in colitis mice colons." (PMID 36479296, 2022). "Our experiment showed that DSS-induced colitis decreased the mRNA expressions of Occludin, ZO-1, E-cadherin, and MUC2 in colon tissue, which could be reversed by GC-K treatment." (PMID 36578000, 2022). "Consistently, here in our study, we discovered that SM934 reduced the intestinal epithelial permeability and restored the aberrant expressions of E-cadherin, β-catenin, and occludin; at the same time, the abnormal epithelial cell proliferation was also inhibited in colitis mice." (PMID 36120344, 2022). "We propose that the effects of corylin on DSS-induced colitis mice are related to the regulation of the colonic mucosal barrier function, where the expression levels of claudin-1, ZO-1, and occludin play important roles in maintaining the intestinal mucosal barrier function." (PMID 35269806, 2022). "TNBS-induced colitis in mice treated with hUC-MSCs resulted in mild occludin and ZO-1 levels." (PMID 36104756, 2022). "After intervention with L. gasseri JM1 and mesalazine, this phenomenon was alleviated in mice with colitis, and the mRNA expression levels of both Occludin and ZO-1 were effectively increased, which prevented the destruction of the intestinal barrier to maintain barrier integrity." (PMID 36615796, 2022). "And promoting occludin expression had proven to be an effective treatment for experimental colitis." (PMID 36185687, 2022).
colitis (continued). "longum CECT 7894 improved the efficacy of IFX for DSS-induced colitis as evidenced by decreased weight loss, disease activity index (DAI) scores, colon length shortening, histological damage, increased ZO-1, and Occludin expressions as compared with mice that received IFX only." (PMID 35979230, 2022). "In addition, melatonin attenuated intestinal permeability by enhancing the expression of ZO-1 and occludin in colitis mice." (PMID 35116024, 2021). "Mice with DSS-induced colitis used in this study consistently showed decreased expression of ZO-1, occludin, MUC2, and MUC13, and elevated level of plasma LPS, indicating an impairment of intestinal barrier functions and thereby increased intestinal permeability." (PMID 33674694, 2021). "The expression of the tight junction (TJ) protein occludin was significantly increased by Gln and Ala-Gln (p < 0.05), indicating that the intestinal barrier was enhanced by Gln and Ala-Gln to alleviate the colitis." (PMID 34046146, 2021). "In accordance with previous studies, the present results indicated that KGM and inulin oligosaccharide could beneficially prevent the DSS-induced down-regulation of ZO-1 and occludin expression, which possibly contribute to their anti-colitis effects." (PMID 35223407, 2021). "Furthermore, the absence of IL-22 completely prevented C. muridarum from alleviating colitis and significantly decreased the levels of occludin, an important downstream effector protein of IL-22." (PMID 33381598, 2020). "However, DSS-induced colitis triggered a significant decrease of occludin gene expression, which was prevented by consumption of Emmental cheese, yet not of the cheese matrix." (PMID 32156075, 2020). "To demonstrate that C. muridarum may alleviate DSS-induced colitis via the IL-22/occludin signaling pathway, we used an anti-IL-22 antibody to determine the specific role of IL-22 and occludin." (PMID 33381598, 2020). "However, sinapic acid treatment was able to increase the mRNA expression of claudin-1, occludin, and ZO-1 in the colons of the colitis mice." (PMID 33312339, 2020). "Therefore, we conclude that C. muridarum alleviates colitis induced by DSS via the IL-22/occludin signal pathway." (PMID 33381598, 2020). "The protein expression levels of ZO-1, claudin-5, and occludin were markedly decreased in DSS-induced colitis mice than in normal controls but they were slightly increased after HnAb administration compared with vehicle (IgY)-treated DSS-induced colitis mice." (PMID 33193406, 2020). "Interestingly, treatment with ED amino acids markedly decreased epithelial architectural derangements and restored the expression of occludin, ZO-1, and claudin-1 protein levels in colitis mice." (PMID 32855978, 2020). "Our results showed that the expression of IL-17A target genes OCLN and IL-22 decreased in the colorectum of ArgmyeKO mice during colitis, which likely contributed to disruption of the intestinal barrier integrity thereby aggravating colitis." (PMID 32391010, 2020). "In addition, SLBZS restores the levels of the colon tight junction proteins ZO-1 and occludin, suggesting that it protects colonic barrier integrity and ameliorates the progression of colitis." (PMID 32547403, 2020). "In addition, the WB results showed lower levels of ZO-1 and occludin in colitis tissues from F. nucleatum + DSS-treated mice than in tissues from mice in the other groups." (PMID 32153411, 2020). "The expressions of tight junction (TJ) proteins occludin and claudin 1 were significantly increased by the taxifolin supplementation, indicating that the gut barrier was enhanced by taxifolin to suppress colitis." (PMID 33664740, 2020). "Recently, it was reported in an experimental colitis model that dextran sodium sulfate (DSS) treatment, a chemical agent known to induce colitis, elevated the c-Src-mediated tyrosine phosphorylation of occludin in a phospholipase D2 (PLD2)-mediated pathway in PLD2 knockout mice." (PMID 30115904, 2018).
colitis (continued). "Since tight junction protein expression and distribution patterns are the main determining factors for gut barrier function, the upregulation by SAA of the expression of genes coding for tight junction proteins (ZO-1, occludin) provides another explanation for SAA anti-colitis effects." (PMID 29921812, 2018). "Our findings are not consistent with those of a previous study that showed that the occludin and ZO-1 expression levels were decreased in the dextran sodium sulfate-induced model of colitis; this effect was significantly inhibited by pyrrolidine dithiocarbamate (PDTC), an inhibitor of NF-κB48." (PMID 27767041, 2016). "Therefore, constitutively high Occludin and Claudin-1 protein expression levels in the large intestine are likely to be attributed the reduced susceptibility to DSS-induced colitis in mPer2m/m mice." (PMID 24845399, 2014). "This hypothesis is consistent with recently published data regarding the antrum mucosal protein (AMP)-18 that ameliorates DSS colitis in mice and also enhances accumulation of occludin and ZO-1 in TJ domains in vitro." (PMID 18074031, 2007). "Intestinal tight junction proteins, such as occludin and ZO-1, are essential mechanical barrier molecules to maintain intestinal mucosal integrity and regulate intestinal permeability, which are the first protective layer against the occurrence and development of colitis." (PMID 40041493, 2025). "Interestingly, this pathogenic role of decreased PER2 in human IBD appears to contrast with findings in mouse models, where mice with a mutated Per2 gene showed increased expression of tight junction proteins (occludin and claudin-1) and decreased susceptibility to DSS-induced colitis." (PMID 40332348, 2025). "Tight junction proteins (ZO-1, occludin, and claudin) are major factors influencing changes in the intestinal epithelial barrier in UC; the increase in tight junction protein levels helps maintain the structural integrity of the intestinal barrier, thereby preventing colitis." (PMID 40542404, 2025). "Similarly, occludin and ZO‐1 mRNA levels were significantly reduced in SqorCKO colitis mice." (PMID 40661137, 2025). "In addition, the protein expression level of OCLN decreased in DSS-induced colitis." (PMID 40227441, 2025). "Additionally, in mice with DSS-induced colitis, syringic acid at doses of 25 and 50 mg/kg prevented colon damage, alleviated proptosis, and increased the mRNA expression of intestinal barrier proteins (claudin-1, ZO-1, and occludin)." (PMID 38732594, 2024). "Similarly, our in vitro findings revealed that PD treatment lowered inflammatory factor release while enhancing intestinal epithelial barrier function by maintaining the level of TJ protein ZO-1 and occludin, suggesting its potential to mitigate injury caused by DSS-induced colitis." (PMID 39877390, 2024). "In addition, the protein expression levels of ZO-1 and occludin decreased in DSS-induced colitis." (PMID 38790680, 2024). "Importantly, the weakened gut barrier in the colitis mice markedly recovered after transplantation of the SH‐modulated gut microbiota, as reflected by the upregulated expression of Occludin, Claudin‐2, Claudin‐3, and Claudin‐4 mRNAs and Occludin, Claudin‐3, and Claudin‐4 proteins." (PMID 38882491, 2024). "The reduced levels of Occludin and ZO‐1 caused by DSS were markedly reversed after the treatment of MAFB overexpression, proving that the upregulation of MAFB could inhibit DSS‐induced intestinal barrier impairment in colitis mice." (PMID 39172054, 2024). "Likewise, in the current study, the downregulated tissue levels of TJ proteins, including ZO-1, occludin, claudin loss off microscopic AJ, TJ, DS, and the microvilli that constitute the brush border in DSS-induced colitis mice, were considerably improved by SGPs." (PMID 37836386, 2023).
colitis (continued). "Therefore, we propose that the effects of corylin on AOM/DSS-induced colitis mice are related to the regulation of the colonic mucosal barrier function, where the expression levels of claudin-1, ZO-1, and occludin play important roles in maintaining the intestinal mucosal barrier function." (PMID 35269806, 2022). "Consequently, CNQX can inhibit the intestinal inflammatory response in mice with colitis, inhibit the mucosal barrier injury, increase the expression of tight junction proteins (including occludin and claudin‐1) and decrease the expression levels of MyD88, TLR4 and MD2." (PMID 34184406, 2021). "The results showed that FPH could significantly increase the protein expressions of ZO-1 and occludin in colon tissues of the DSS-induced colitis mouse model, indicating the strengthening function of FPH on the gut barrier, which was consistent with the H&E staining result." (PMID 34966476, 2021). "In addition to the anti-inflammatory effect, strengthening the tight junction might be another mechanism involved in the anti-colitis effect of PS23 FM through increases in occludin synthesis and short-chain fatty acid production." (PMID 34681392, 2021). "Furthermore, we demonstrated that Kae could markedly restore the expression of ZO-1, occludin, and claudin-1 in the murine colitis model, likely recovering the integrity of the intestinal mucosal barrier." (PMID 34367139, 2021). "Therefore, IL-22/occludin signal pathway plays an important role in colitis." (PMID 33381598, 2020). "Furthermore, a few in vivo studies found that the application of F. prausnitzii or R. intestinalis in experimental murine colitis models improved the epithelial barrier, as shown by increased occludin expression in colonic tissue and lower FITC–dextran levels in serum samples." (PMID 32731411, 2020). "Therefore, IL-22/occludin signal pathway is important in colitis." (PMID 33381598, 2020). "Furthermore, a recent study in colitis mice demonstrated the effect of sodium propionate to ameliorate dextran sulphate sodium-induced colitis and improve intestinal barrier function by inhibiting the decrease of ZO-1 and occludin expression in the colonic tissue." (PMID 30128177, 2018). "Furthermore, TER might have a protective effect on barrier integrity by maintaining the expression of ZO-1 and occludin, thereby decreasing the severity of colitis." (PMID 28553294, 2017). "However, it remains to be determined whether Occludin and Claudin-1 expression change are indeed primarily responsible for daily changes of tight junction permeability and susceptibility to DSS-induced colitis." (PMID 24845399, 2014). "Interestingly, in PBS-treated mice with subsequent induction of colitis (DSS/PBS) or in Lc-treated mice with subsequent induction of colitis (DSS/Lc) was a substantial loss of occludin in colon but not in terminal ileum." (PMID 22132181, 2011). "In a dextran sulfate sodium (DSS)-induced colitis mouse model, HMCM administration enhanced the expression of tight junction proteins (Claudin, ZO-1, Occludin) and repaired the damaged intestinal barrier." (PMID 41732380, 2026). "Compared to the normal group, the colitis mice exhibited significantly increased mRNA expression levels of epithelial barrier proteins (CLDN-2, occludin, and ZO-1) as well as the mucin barrier protein (MUC2) in their colon tissues." (PMID 40529132, 2025). "Studies have shown that 5-ASA treatment alleviates dextran sulfate sodium (DSS)-induced colitis in mice and significantly increases the protein expression levels of junctional adhesion molecule-A (JAM-A) and Occludin." (PMID 41140699, 2025). "In the DSS-induced colitis model, HMGB1 overexpression was accompanied by downregulation of the barrier proteins Occludin, E-cadherin, and Claudin-1, which was reversed by DPG intervention, as further corroborated by immunofluorescence staining results." (PMID 40689397, 2025).